ILK (integrin linked kinase)
Diseases named in the same sentence as ILK in open-access papers (continued):
Sharing a sentence is not in itself a finding about the gene and the disease.
lung carcinoma (continued). "We provide evidence that the PARVA-mediated regulation of these functions in lung cancers occurs through the activation of ILK, although we cannot exclude other pathways that may also contribute to these effects." (PMID 25738875, 2015). "To further understand how rVP1 could reduce expression of COX-2, we next examined whether ILK or the IKK/NF-κB pathway plays any role in the inhibitory effect of rVP1 on COX-2 expression in lung cancer cells." (PMID 25004182, 2014). "In this study, our in vitro results show, for the first time, a participation of the widespread β1-integrin subunit-associated protein kinases, ILK, PKBα/Akt, GSK-3β within the radiation response of a human lung cancer cell line as well as normal human lung primary fibroblasts." (PMID 12778079, 2003). "However, whether the knockdown of ILK affects growth and apoptosis of lung cancer cells remains to be elucidated." (PMID 25760437, 2015). "Importantly, whether downregulation of ILK increases the sensitivity of lung cancer cells to cisplatin and amplifies cell apoptosis also remains to be elucidated." (PMID 25760437, 2015). "In lung cancer cells, there is evidence that FAK mediates PTTG-induced EMT whereas, in mammary cells, ILK function is required for TGF-β1-induced EMT." (PMID 35682554, 2022). "In addition, ILK could regulate cell metastasis through NF-κB signaling in lung cancer." (PMID 33854551, 2021). "Downregulation of ILK expression and CDDP treatment, in combination, is a more effective approach for the treatment of lung cancer through affecting downstream gene expression, including p-GSK3β, p-AKT, AP-1, β-catenin, cyclin D1 and MMP-9." (PMID 25760437, 2015). "Further studies indicate that silencing ILK through targeting small interfering RNA (siRNA) inhibits cell proliferation and growth, induces cell cycle arrest and the apoptosis of bladder and pancreatic cancer cells, suggesting the inhibition of ILK may be a novel approach for treating lung cancer." (PMID 25760437, 2015). "Overexpression of ILK or NF-κB p65 blocked the inhibitory effect of rVP1 on COX-2 expression to induce MIG-7, EMT and MMP2 activity as well as invasiveness of lung cancer cells." (PMID 25004182, 2014). "To elucidate the mechanism by which rVP1 acts on the integrin β1/Akt signaling of lung cancer cells, we examined the effects of rVP1 on integrin downstream targets, PI3K, PIP3, ILK and Akt." (PMID 25004182, 2014). "Overexpression of ILK in lung cancer cells results in the upregulation of PINCH1, β-parvin, and Ras suppressor protein 1 (RSU1) expression, while pharmacologic inhibition of ILK in KRAS-mutant lung cancer cells suppressed cell growth, migration, and EMT." (PMID 35804980, 2022). "Consistent with the reported effect of IL-6 on MUC1 overexpression in breast and lung cancer cells, exposure of AsPC-1 cells to IL-6 led to parallel increases in STAT3 phosphorylation and the expression of MUC1-C, and, to a lesser extent, ILK." (PMID 28692035, 2017). "We found that overexpression of ILK by transfection of ILK plasmid (pILK) in H1299 and CL1-5 lung cancer cells increased phosphorylation of AktS473, IKKα/βS176/180 and NF-κB p65S536 as well as degradation of IκB, which were positively correlated with elevation of COX-2 level." (PMID 25004182, 2014). "Thus, it is hypothesized that there may be a synergistic interaction between downregulation of ILK and CDDP administration for treating lung cancer by creating cytotoxic DNA lesions and affecting apoptosis in lung cancer A549 cells." (PMID 25760437, 2015). "Nevertheless, our data showed that PAK1 might not interact with ILK in lung cancer cells even though silencing PAK1 decreased the PARVA-induced phosphorylation of ILK at Ser246." (PMID 25738875, 2015).
melanoma (20 papers, 2004 to 2025). A malignant, usually aggressive tumor composed of atypical, neoplastic melanocytes. "TSPAN8 was shown to function as a negative regulator of integrin-linked kinase driven β1 integrin-dependent adhesion in melanoma cells, thereby decreasing adhesive interaction with the surrounding matrix environment and promoting tumor invasiveness." (PMID 36922633, 2024). "Due to the heterogeneity of different tumors, JWA mainly inhibits the formation of blood vessels in melanoma by down-regulating the integrin-linked kinase (ILK) signaling pathway through suppressing intergrin αvβ3 and transcription factor SP1 expression." (PMID 36230577, 2022). "The present study is aimed at exploring the effects of CQ alone or in combination with silencing of ILK on melanoma cells and pathways associated with these treatments, as well as identifying potential molecular targets for melanoma treatment." (PMID 33916175, 2021). "The integrin-linked kinase (ILK) is a key regulator of cell-matrix adhesion, which interacts with the cytoplasmic domain of β1 integrin subunit and plays a crucial role in melanoma progression." (PMID 28188308, 2017). "In fact, a high activation of ILK is associated with poor outcome in patients with melanoma." (PMID 24743186, 2014). "ILK silencing led to a decrease in the expression of N-cadherin, which in turn inhibited the invasion potential of melanoma cells by reducing endothelium adhesion and transendothelial migration." (PMID 41155412, 2025). "On the other hand, many Rab proteins also participate in the regulation of the Akt/GSK-3β pro-survival signaling pathway in melanoma cells, which was also downregulated following ILK knockdown." (PMID 41155412, 2025). "JWA combined with ILK or ING4 can better predict prognosis in melanoma patients compared with indicators alone." (PMID 36230577, 2022). "In melanoma cells, siRNA-mediated depletion of ILK suppresses the expression of N-cadherin, showing that ILK is involved in cadherin switch, a hallmark of EMT." (PMID 35804980, 2022). "For instance, ILK expression is higher in brain, breast, colorectal, gastric, head and neck, kidney, liver, lymphoma, melanoma, myeloma, ovarian, pancreatic, prostate, sarcoma cancers in some datasets." (PMID 35692780, 2022). "Curiously, we have shown recently that thymosin β4 locates to FAs in melanoma cells, where ILK is found pointing at ILKs and thymosin β4 potential interaction in melanoma cells." (PMID 35089438, 2022). "In our previous work, we showed that ILK silencing reduces the migration of melanoma cells in the Boyden chamber and also decreases transendothelial cell migration." (PMID 33916175, 2021). "Both studied melanoma cells exhibit a high level of basal autophagy but respond differently to the knockdown of ILK." (PMID 33916175, 2021). "Elevated ILK expression and activity contributes to increased proliferation and invasive potential of melanoma cells." (PMID 33916175, 2021). "The knockdown of ILK seems to activate autophagy more in the early stages of melanoma development than in metastatic cells." (PMID 33916175, 2021). "The results show that silencing of ILK significantly reduced (by about 60%) wound closure after 24 h in both melanoma cell lines." (PMID 33916175, 2021). "We have previously shown that ILK silencing has anti-tumor implications for both melanoma and bladder cancer." (PMID 33916175, 2021). "Chloroquine also inhibits the growth and survival of melanoma cells to a similar extent as ILK silencing." (PMID 33916175, 2021). "Our previous studies have revealed the important role of ILK in melanoma EMT and particularly in the regulation of N-cadherin expression by modulation of the expression of Rab proteins associated with N-cadherin endocytosis, degradation, or recycling." (PMID 33916175, 2021). "Our data show that ILK knockdown by siRNA suppresses melanoma cell growth by inducing autophagy through AMPK activation, and simultaneously initiates apoptosis." (PMID 33916175, 2021).
melanoma (continued). "To evaluate the effects of CQ and knockdown of ILK on melanoma cell migration, we performed a scratch wound healing assay." (PMID 33916175, 2021). "We demonstrated that inhibition of ILK expression and activity using siRNA has antitumor effects in melanoma and bladder cancer." (PMID 33916175, 2021). "Our data are the first to establish Tspan8 as a negative regulator of ILK activity, thus inhibiting β1 integrin-mediated anchorage to matrix required for allowing melanoma invasion." (PMID 28188308, 2017). "Tspan8 expression in invasive melanoma cells was responsible for inhibition of ILK phosphorylation and its downstream target Akt-S473, concomitantly with reduced adhesiveness." (PMID 28188308, 2017). "These in vitro findings have in vivo significance, since we found that the expression of Tspan8 is inversely correlated with ILK phosphorylation in melanoma xenografts and in human melanocytic lesions." (PMID 28188308, 2017). "Altogether, the in vitro, in vivo and in situ data highlight a novel regulatory role for Tspan8 in melanoma progression by modulating cell-matrix interactions through β1 integrin-ILK axis and establish Tspan8 as a negative regulator of ILK activity." (PMID 28188308, 2017). "It was described that the integrin-linked kinase ILK, which correlates with melanoma progression and invasion, enhances the activity of NF-κB and thereby leads to the secretion of IL-6 and VEGF in melanoma cells." (PMID 26000250, 2015). "On the other hand, increased expression of integrin-linked kinase and phospho-Akt in the PI3 kinase survival pathway has been observed in melanoma and correlated with tumour thickness and 5-year patient survival." (PMID 16755297, 2006). "The only other report of EGF and TGFβ1 effects on ILK expression, showed stimulation of ILK expression in a human melanoma cell line following exposure to EGF and TGFβ1 for 24 and 48 hours." (PMID 16643659, 2006). "Recently, we demonstrated that the integrin linked kinase (ILK), a direct regulator of AKT activity, is overexpressed in melanoma and increased ILK expression is correlated with melanoma thickness and 5-year patient survival." (PMID 15305193, 2004). "For instance, integrin-linked kinase (ILK) regulates N-cadherin expression at the post-transcriptional level by modulating the expression of Rab proteins engaged in endocytosis, recycling, and lysosomal degradation in melanoma cells." (PMID 41155412, 2025). "For this reason, we decided to use CQ, which has been reported to exert anticancer effects on melanoma and other tumors, in combination with silencing of ILK (integrin-linked kinase) to strengthen siILK-caused inhibition of pro-survival signaling with CQ-driven autophagy inhibition." (PMID 33916175, 2021). "In our study, we demonstrated that silencing of ILK induced autophagy much more frequently in the early stage of melanoma compared to metastatic, and it may lead independently to cell death or act as a precursor of apoptosis." (PMID 33916175, 2021). "The fact that Tspan8 expression interfered only with Akt-S473 and not with Akt-T308 phosphorylation suggests that Tspan8 restricts full Akt activity in melanoma cells through inappropriate ILK activation, leading to attenuation of β1-integrin adhesive function." (PMID 28188308, 2017). "Indeed, Tspan8 impairs integrin-mediated anchorage of melanoma cells to matrix components by negatively regulating ILK activity, leading to the inhibition of its downstream target Akt-S473 and β1 integrin clustering." (PMID 28188308, 2017). "Finally, we observed a tumor-promoting effect of Tspan8 in vivo and a mutually exclusive expression pattern between Tspan8 and phosphorylated ILK in melanoma xenografts and human melanocytic lesions." (PMID 28188308, 2017). "Thus, our study identified Tspan8 as a novel regulator of ILK-driven β1 integrin signaling, mediating low interactions of melanoma cells with the surrounding extracellular microenvironment, mandatory for tumor escape." (PMID 28188308, 2017).
melanoma (continued). "We have previously demonstrated that EMT markers in melanoma cells are dependent on ILK function." (PMID 27683053, 2016). "In our earlier work, we suggested that ILK may mediate cross-talk between adhesion molecules in melanoma cells and the control of cadherin expression by integrins might be a general feature common to all motile cells." (PMID 27683053, 2016). "We had similar results after silencing the ILK in melanoma cells." (PMID 27683053, 2016). "We also demonstrated that vimentin expression was sufficient to induce increased mesenchymal/pro-metastasic phenotypic changes in melanoma cells, including ILK/GSK3-β-dependent E-cadherin down-regulation, Snail1 activation and increased cell motility and migration." (PMID 23785295, 2013). "In addition, the combined expression of JWA and ILK could better predict the prognosis of melanoma, and the combined expression of JWA and MMP2 in gastric cancer could also better predict the prognosis of gastric cancer." (PMID 36230577, 2022). "Moreover, Tspan8 promotes in vivo orthotopic tumor growth and an inverse pattern of Tspan8 and P-ILK expression was observed in melanoma xenografts as well as in human melanocytic lesions, underscoring the ability of Tspan8 to modulate ILK function in cutaneous microenvironment." (PMID 28188308, 2017). "JWA inhibits the metastasis of melanoma and gastric cancer cells by inhibiting the expression of the transcription factor SP1 and intergrin αvβ3 through suppressing the ILK and MMP2 signaling pathways." (PMID 36230577, 2022). "In the more advanced melanoma cell line 1205Lu, we observe a markedly higher increase of ULK expression after silencing of ILK." (PMID 33916175, 2021). "ILK knockdown decreased ULK1 phosphorylation at S757, which probably enabled its interaction with AMPK in the melanoma cell line WM793." (PMID 33916175, 2021). "The two mRNA isoforms of ILK (ILK1 and ILK2), share similar structural and functional properties but, whereas ILK1 is expressed in all normal tissues, ILK2 has only been identified in two highly metastatic fibrosarcoma and melanoma cell lines." (PMID 16643659, 2006). "The increased level of cleaved Poly (ADP-ribose) polymerase (PARP1) indicates that apoptosis may contribute to cell death after silencing of ILK at least in WM793 and early-stage melanoma cells." (PMID 33916175, 2021). "Interestingly, high ILK and low NICD levels are detected in basal cell carcinoma and melanoma patients." (PMID 19468305, 2009). "Interestingly, Tspan8 ablation significantly affected ILK activation in melanoma cells adhering to the matrix but not FAK autophosphorylation." (PMID 28188308, 2017). "Although the implication of Rictor in melanoma cells awaits further studies, we clearly demonstrate that in the absence of Tspan8, ILK-dependent Akt-S473 phosphorylation in response to ligation of β1 integrins occurs efficiently, leading to integrin clustering." (PMID 28188308, 2017).
cardiomyopathy (19 papers, 2008 to 2024). A disease of the heart muscle or myocardium proper. "Previously accumulation of evidence identified that ILK was associated with some cardiomyopathy phenotypes, as well as involved in cardiac remodeling." (PMID 36935650, 2022). "ILK has a vital function during fetal development and tissue homeostasis, and ILK dysregulation has been associated with cardiomyopathies and different types of cancer in humans." (PMID 33854551, 2021). "For instance, the zebrafish mutant line main squeeze was shown to carry a mutation in the Integrin-linked kinase (ILK) gene resulting in reduced PKB/Akt phosphorylation, defective cardiac stretch sensor function and thereby severe cardiomyopathy in zebrafish." (PMID 29699591, 2018). "Accordingly, dysregulation of ILK has been observed in many human pathologies, including cancers and cardiomyopathies." (PMID 24314125, 2014). "Our study therefore suggests that ILK gene therapy beneficially affects left ventricular structure and function in doxorubicin-induced cardiomyopathy, as well as improving survival." (PMID 22348065, 2012). "Targeted knock-out of ILK in the murine heart results in disaggregation of cardiomyocytes and spontaneous dilated cardiomyopathy, suggesting that ILK plays an important part in protecting the heart from cardiomyopathy and heart failure." (PMID 22348065, 2012). "In the present study, we have similarly found that ILK treatment improves cardiac function secondary to reduced apoptosis in doxorubicin-induced cardiomyopathy." (PMID 22348065, 2012). "This evidence supports the rationale of our central hypothesis and our findings that liraglutide weakens cardiomyopathy streptozotocin-induced diabetes through the modulation of the ILK and PI3K/AKT/PTEN pathway." (PMID 38543160, 2024). "Also, the crucial role of ILK in the cardiovascular system has been reported, particularly in processes of neovascularization and cardiomyogenesis, which is additionally supported by the fact that mutations in the ILK gene may be linked with cardiomyopathy in humans." (PMID 35089438, 2022). "Intragenic-DMGs at 0.8% CO2 vs. 0.4% and 0.1% included: PDLIM7, whose resulting protein regulates valve annulus size and hemostasis; TGFB1, which regulates postnatal cardiomyocyte differentiation; and ILK, which has been shown to exhibit protective effects against cardiomyopathy." (PMID 33193638, 2020). "Another ILK mutant line, lost contact (loc), also displays a cardiomyopathy phenotype." (PMID 29911105, 2018). "To further investigate the Hsp/c70 dependent cardioprotective effect of ILK we used Doxorubicin (DOX), an effective and frequently used chemotherapeutic agent for various malignancies, which causes both an acute and late-onset, dose-limiting cardiomyopathy." (PMID 24260102, 2013). "Our study suggests that fine-tuning of such an HSR through neuroendocrine signals can regulate normal physiological processes such as stress responses and aging, and may thus be relevant to ILK-mediated, age-related pathologies such as cancer and cardiomyopathies." (PMID 24314125, 2014). "The present study provides evidence of benefit for ILK treatment on the progression of heart failure caused by doxorubicin-induced cardiomyopathy, a non-ischemic cardiomyopathy whose pathophysiological features closely resemble those of dilated cardiomyopathy in humans." (PMID 22348065, 2012). "A large animal model of pacing-induced cardiomyopathy showed inhibition of the LXR/RXR pathway, activation of the ILK pathway, and increased inflammatory cytokines, apoptosis and fibrosis." (PMID 36928240, 2023).
cardiomyopathy (continued). "By contrast, other pathways clearly showed opposite trends, such as oxidative phosphorylation, necroptosis signaling, GP6 signaling in SDM, or fatty acid oxidation, ILK and RHOA signaling, and cardiomyopathy signaling pathway in LDM." (PMID 36835504, 2023). "Despite identification of several potential drug targets in the ILK signaling pathway, pharmacological treatment strategies to restore contractile function in ILK-dependent cardiomyopathies have not been established yet." (PMID 30463267, 2018). "ILK adenoviral gene therapy has been shown to improve remodeling in a rat MI model through upregulation of vascular endothelial growth factor-mediated angiogenesis, and to protect against adverse remodeling in chronic DOX-induced cardiomyopathy." (PMID 24260102, 2013).